SGCA (sarcoglycan alpha)
Description:
Component of the sarcoglycan complex, a subcomplex of the dystrophin-glycoprotein complex which forms a link between the F-actin cytoskeleton and the extracellular matrix.
Synonyms: 50DAG; ADL; DAG2; SCARMD1; LGMD2D; adhalin; DMDA2; A2; LGMDR3
Tractability: Antibody: its Gene Ontology location is reachable by antibodies, with high confidence; UniProt places it where antibodies can reach, with medium confidence; UniProt predicts a signal peptide or a membrane-spanning region.
Gene: Protein-coding gene on chromosome 17 (50,164,214 to 50,175,935, forward strand). Ensembl gene ENSG00000108823.
Subcellular location: Cell membrane, sarcolemma; Cytoplasm, cytoskeleton
Pathways (Reactome):
Extracellular matrix organization: Formation of the dystrophin-glycoprotein complex (DGC)
Gene Ontology:
Molecular function: protein binding; calcium ion binding
Biological process: camera-type eye development; muscle contraction; muscle organ development
Cellular component: dystrophin-associated glycoprotein complex; endoplasmic reticulum membrane; Golgi membrane; neuromuscular junction; plasma membrane; sarcoglycan complex; cell-cell junction; cytoskeleton; dystroglycan complex; membrane; membrane raft; sarcolemma
Genetic constraint (gnomAD): Loss-of-function variants: 34 observed, 35.56 expected, observed/expected ratio (o/e) 0.96, 90% interval 0.73 to 1.27. The upper end of that interval is the gene's LOEUF score, 1.27, which puts it in group 5 of 6, group 1 being the genes least tolerant of losing a copy. Missense variants: 476 observed, 516.36 expected, observed/expected ratio (o/e) 0.92, 90% interval 0.85 to 0.99. Synonymous variants: 209 observed, 209.56 expected, observed/expected ratio (o/e) 1, 90% interval 0.89 to 1.12.
Gene-disease validity (ClinGen):
ClinGen rates the evidence that SGCA causes each of these diseases.
autosomal recessive limb-girdle muscular dystrophy (autosomal recessive): Definitive. Autosomal recessive form of limb-girdle muscular dystrophy.
Homologues: Orthologues: chimpanzee SGCA (98% identical), macaque SGCA (97% identical), dog SGCA (90% identical), pig SGCA (90% identical), mouse Sgca (89% identical), rat Sgca (87% identical), guinea pig SGCA (84% identical), rabbit SGCA (76% identical), tropical clawed frog sgca (50% identical), zebrafish sgca (40% identical), Caenorhabditis elegans sgca-1 (23% identical), Drosophila melanogaster Scgalpha (21% identical). Paralogues in human: SGCE (44% identical).
Diseases named in the same sentence as SGCA in open-access papers:
SGCA is named in the same sentence as 43 diseases in open-access papers, as found by Europe PMC text mining. Sharing a sentence is not in itself a finding about the gene and the disease. The quoted sentences say what the papers report.
sarcoglycanopathies (15 papers, 2008 to 2026). "Sarcoglycanopathies (SGPs) are autosomal recessive limb-girdle muscular dystrophies (LGMDs) caused by mutations in four genes: SGCA, SGCB, SGCG, and SGCD, which lead to α-SGP (LGMDR3), β-SGP (LGMDR4), γ-SGP (LGMDR5), and δ-SGP (LGMDR6), respectively." (PMID 39755676, 2025). "Sarcoglycanopathies (SGPs) are limb-girdle muscular dystrophies (LGMDs) that can be classified into four types, LGMDR3, LGMDR4, LGMDR5, and LGMDR6, caused by mutations in the genes, SGCA, SGCB, SGCG, and SGCD, respectively." (PMID 39755676, 2025). "Sarcoglycanopathies are caused by mutations in the SGCA, SGCB, SGCG, and SGCD genes that code for α-, β-, γ-, and δ-sarcoglycan (SG), respectively." (PMID 41009401, 2025). "Sarcoglycanopathies are caused by mutations which occur in LGMD genes SGCA, SGCB, SGCG, and SGCD that lead to misfolding, truncated, or loss of protein of α, β, γ, and δ protein which stabilizes the sarcolemma of muscle cells." (PMID 40225150, 2023). "Sarcoglycanopathies include four subtypes of autosomal recessive limb-girdle muscular dystrophies (LGMDR3, LGMDR4, LGMDR5 and LGMDR6) that are caused, respectively, by mutations in the SGCA, SGCB, SGCG and SGCD genes." (PMID 34515763, 2022). "Sarcoglycanopathies are caused by mutations, mostly missense, in the SGCA, SGCB, SGCG, and SGCD genes." (PMID 34110586, 2021). "Sarcoglycanopathies (R3-R6) are caused by missense mutations of SGCA, SGCB, SGCG, and SGCD genes, that result in misfolding of the four corresponding sarcoglycan protein subunits that form the sarcoglycan complex in the sarcolemma of muscle cells." (PMID 34110586, 2021). "Among them are sarcoglycanopathies caused by mutations in at least four genes named SGCA, SGCB, SGCG and SGCD." (PMID 28883879, 2017). "Mutations in the α- (SGCA), β- (SGCB), γ- (SGCG), and δ- (SGCD) SG genes cause the four sarcoglycanopathies termed LGMD R3, R4, R5, and R6, respectively." (PMID 40549548, 2025). "Sarcoglycanopathies (SG) are the most frequent form of autosomal recessive LGMD comprising of four subtypes, LGMDR3, LGMDR4, LGMDR5, and LGMDR6, caused by mutations in SGCA, SGCB, SGCG, and SGCD encoding for the alpha-, beta-, delta-, and gamma-sarcoglycan proteins, respectively." (PMID 40225150, 2023). "In a study performed on 20 Turkish patients, calpainopathy was the most prevalent form, and dysferlinopathy was the least form of LGMDs, and among sarcoglycanopathies, the mutation in the SGCG gene was the most common and in the SGCA gene was the least common form." (PMID 31937337, 2020). "This study expands the clinical and genetic spectrum of sarcoglycanopathies in Chinese patients and provides evidence that disease severity of LGMD2D may be predicted by α-sarcoglycan expression and SGCA mutation." (PMID 30764848, 2019). "Sarcoglycanopathies comprise four subtypes of autosomal recessive limb-girdle muscular dystrophy (LGMD2C, LGMD2D, LGMD2E, and LGMD2F) that are caused, respectively, by mutations in the SGCG, SGCA, SGCB, and SGCD genes." (PMID 30764848, 2019). "The sarcoglycanopathies are a severe form of limb girdle muscular dystrophy caused by mutations in the sarcoglycan genes SGCA, SGCB, SGCG, and SGCD, leading to reduced or absent expression of the alpha-, beta-, gamma-, and delta-sarcoglycan proteins respectively." (PMID 40129306, 2025).
muscular dystrophies (12 papers, 2009 to 2025). "Loss-of-function mutations in SGCA, encoding α-sarcoglycan, cause limb-girdle muscular dystrophy 2D/R3, an early-onset, severe, and rapidly progressive form of muscular dystrophy affecting both male and female patients." (PMID 33848270, 2021). "SGCA (sarcoglycan alpha) has been associated with muscular dystrophies." (PMID 39480826, 2024). "An automated process has been developed for the detection of deletions, duplications/insertions and point mutations in any gene or family of genes and has been applied to ten genes known to bear mutations that cause muscular dystrophy: DMD; CAV3; CAPN3; FKRP; TRIM32; LMNA; SGCA; SGCB; SGCG; SGCD." (PMID 19835634, 2009). "Also, there were no CNVs detected in the targeted analysis of SGCA, SGCB, SGCG, SGCD, and FKRP genes for other frequent limb-girdle muscular dystrophies." (PMID 36425804, 2022).
limb-girdle muscular dystrophy (6 papers, 2009 to 2025). Limb-girdle muscular dystrophy (LGMD) is a heterogeneous group of muscular dystrophies characterized by proximal weakness affecting the pelvic and shoulder girdles. "Mutations in SGCE cause myoclonus-dystonia syndrome and penetrance is influenced by paternal expression of the gene, while defects in SGCA cause limb girdle muscular dystrophy." (PMID 19503617, 2009). "For these individuals, mutation analysis was extended to include the seven most common limb-girdle muscular dystrophy (LGMD) genes (DYSF, CAPN3, SGCA, SGCB, SGCC, SGCD, and FKRP)." (PMID 31588416, 2017).
autosomal recessive limb-girdle muscular dystrophies (4 papers, 2019 to 2025). "Another baby had a pathogenic variant in the SGCA gene associated with autosomal recessive limb girdle muscular dystrophy." (PMID 36278620, 2022).
cardiomyopathies (2 papers, 2021 to 2025). "Sarcoglycan genes are associated with dystrophin and cardiomyopathies, including SGCA which encodes α component and was reported in relation to mild cardiomyopathies in the α-sarcoglycan-deficient mouse model." (PMID 33567613, 2021).
Ehlers-Danlos syndrome (1 paper, 2024). The Ehlers–Danlos syndromes (EDS) are a clinically and genetically heterogeneous group of heritable connective tissue disorders (HCTDs) characterized by joint hypermobility, skin hyperextensibility, and tissue fragility. "The gene ontologies for list 8+ linked CDC42EP2, FOXF1, SGCA, and SORBS1 to Megacystis-Microcolon-Intestinal Hypoperistalsis Syndrome while CDC42EP2 and CNN1 linked to Classical-like Ehlers-Danlos Syndrome." (PMID 39480826, 2024).
limb-girdle muscular dystrophy type 2D (1 paper, 2025). "Mutations in SGCA are known to be able to cause limb-girdle muscular dystrophy type 2D (LGMD2D), and SGCA has also been included in a 16-gene signature developed by computational analysis for distinguishing rheumatoid arthritis from OA." (PMID 41035938, 2025).
Megacystis (1 paper, 2024). Dilatation of the bladder postnatally. "We propose that CDC42EP2, FOXF1, SGCA, and SORBS1 are novel genes in Megacystis-Microcolon-Intestinal Hypoperistalsis Syndrome." (PMID 39480826, 2024).
progressive muscular dystrophy (1 paper, 2017). "While SGCA-null mice display progressive muscular dystrophy, but no cardiac abnormalities." (PMID 28797108, 2017).
weakness (1 paper, 2024). "In Austria, the most frequent cause of limb-girdle muscular weakness and hereditary myopathy were pathogenic variants in CAPN3, FKRP, ANO5, DYSF, SGCA." (PMID 38758368, 2024).
cancer (6 papers, 2022 to 2025). A tumor composed of atypical neoplastic, often pleomorphic cells that invade other tissues. "Soluble guanylate cyclase activators (sGCa) represent a promising therapeutic strategy for managing cardiovascular and renal dysfunction in patients with CKM syndrome, particularly when combined with cancer care." (PMID 40227756, 2025).
tumor (3 papers, 2024 to 2025). "Conversely, among the four downregulated genes (KANK2, SGCA, SLC12A4, and MEIS1), higher expression correlated with better prognosis, suggesting their potential tumor-suppressive roles." (PMID 40525903, 2025).
genetic diseases (1 paper, 2022). "Overall our results describe a new therapeutic avenue for the treatment of LGMD R3 patients carrying missense mutations of SGCA but also other genetic diseases sharing similar protein degradation defects as LGMD R5 and CF." (PMID 35571097, 2022).
renal disorders (1 paper, 2026). "sGC stimulators (sGCs) and activators (sGCa) are emerging as a potential new approach for the treatment of renal disorders." (PMID 41846889, 2026).
SGCA also shares sentences with these, for which no sentence is quoted: Brody myopathy (2 papers); calpainopathy (2); lung adenocarcinoma (2); albinism (1); Arthritis (1); Becker muscular dystrophy (1); bladder cancer (1); Burkitt lymphoma (1); congenital myopathy (1); cystic fibrosis (1); dermatomyositis (1); dilated cardiomyopathy (1); Duchenne muscular dystrophy (1); dysferlinopathy (1); dystrophinopathy (1); endometriosis (1); hearing loss (1); lung carcinoma (1); Miyoshi myopathy (1); myoclonus-dystonia syndrome (1); myotonic dystrophy (1); neuroblastoma (1); neurofibromatosis (1); Pompe disease (1); prostate carcinoma (1); rhabdomyolysis (1); rhabdomyosarcoma (1); rheumatoid arthritis (1); Spastic paraplegia (1).